ATP13A1 (ATPase 13A1)
Description:
Endoplasmic reticulum translocase required to remove mitochondrial transmembrane proteins mistargeted to the endoplasmic reticulum. Acts as a dislocase that mediates the ATP-dependent extraction of mislocalized mitochondrial transmembrane proteins from the endoplasmic reticulum membrane. Specifically binds mitochondrial tail-anchored transmembrane proteins: has an atypically large substrate-binding pocket that recognizes and binds moderately hydrophobic transmembranes with short hydrophilic lumenal domains.
Synonyms: ATP13A; KIAA1825; CGI-152; FLJ31858
Tractability: Antibody: UniProt predicts a signal peptide or a membrane-spanning region. PROTAC: ubiquitination databases record sites on it; its protein half-life has been measured.
Gene: Protein-coding gene on chromosome 19 (19,645,198 to 19,663,700, reverse strand). Ensembl gene ENSG00000105726.
Subcellular location: Endoplasmic reticulum membrane
Subcellular location (Human Protein Atlas): Vesicles
Pathways (Reactome):
Transport of small molecules: Ion transport by P-type ATPases
Gene Ontology:
Molecular function: membrane protein dislocase activity; protein binding; ABC-type manganese transporter activity; ATPase-coupled monoatomic cation transmembrane transporter activity; P-type ion transporter activity; ATP binding; ATP hydrolysis activity; nucleotide binding; P-type transmembrane transporter activity
Biological process: extraction of mislocalized protein from ER membrane; intracellular calcium ion homeostasis; monoatomic ion transmembrane transport; transmembrane transport; manganese ion transmembrane transport; monoatomic cation transmembrane transport
Cellular component: endoplasmic reticulum membrane; membrane
Genetic constraint (gnomAD): Loss-of-function variants: 55 observed, 116.38 expected, observed/expected ratio (o/e) 0.47, 90% interval 0.38 to 0.59. The upper end of that interval is the gene's LOEUF score, 0.59, which puts it in group 2 of 6, group 1 being the genes least tolerant of losing a copy. Missense variants: 1,389 observed, 1,541.7 expected, observed/expected ratio (o/e) 0.9, 90% interval 0.86 to 0.94. Synonymous variants: 775 observed, 672.31 expected, observed/expected ratio (o/e) 1.15, 90% interval 1.09 to 1.22.
Homologues: Orthologues: chimpanzee ATP13A1 (99% identical), macaque ATP13A1 (99% identical), pig ATP13A1 (96% identical), guinea pig ATP13A1 (95% identical), mouse Atp13a1 (95% identical), rat Atp13a1 (95% identical), dog ATP13A1 (94% identical), tropical clawed frog atp13a1 (76% identical), zebrafish atp13a1 (74% identical), Drosophila melanogaster CG6230 (53% identical), Caenorhabditis elegans catp-8 (52% identical). Paralogues in human: ATP13A4 (25% identical), ATP13A5 (25% identical), ATP13A3 (24% identical), ATP13A2 (24% identical), ATP2A2 (14% identical), ATP2B2 (14% identical), ATP2B1 (14% identical), ATP2A3 (14% identical), ATP2A1 (14% identical), ATP2B3 (14% identical), ATP2B4 (13% identical), ATP2C1 (13% identical), and 9 more.
Diseases named in the same sentence as ATP13A1 in open-access papers:
ATP13A1 is named in the same sentence as 13 diseases in open-access papers, as found by Europe PMC text mining. Sharing a sentence is not in itself a finding about the gene and the disease. The quoted sentences say what the papers report.
celiac disease (1 paper, 2018). An autoimmune genetic disorder with an unknown pattern of inheritance that primarily affects the digestive tract. "These include ATP13A1 with BMI, ERAP2 for both inflammatory bowel disease and celiac disease, RPS26 for both type 1 diabetes and rheumatoid arthritis, and BTN2A1 with schizophrenia." (PMID 30061686, 2018).
Parkinson disease (1 paper, 2022). A progressive degenerative disorder of the central nervous system characterized by loss of dopamine producing neurons in the substantia nigra and the presence of Lewy bodies in the substantia nigra and locus coeruleus. "ATP13A1, encoding for a lysosomal ATPase was correlated with Parkinson’s Disease." (PMID 36362022, 2022).
virus infection (1 paper, 2022). "Loss of ATP13A1 attenuated the expression of antiviral genes upon virus infection." (PMID 36216581, 2022). "The proteases responsible for MAVS degradation are most likely derived from host cells rather than viruses, as MAVS can be restored in ATP13A1‐deficient cells following protease inhibitors treatment without virus infection." (PMID 36216581, 2022). "Moreover, lungs of Atp13a1‐cKO mice showed severe injuries and more infiltration of monocytes than those from the wild‐type mice upon virus infection." (PMID 36216581, 2022).
bacterial infection (1 paper, 2022). "Since the antigen presentation pathways for exogenous ligand and intracellular bacteria differ mechanistically, we also tested the effect of ATP13A1 deficiency on MAIT cell activation in the context of bacterial infection." (PMID 34968463, 2022).
infection (1 paper, 2022). The state of being infected such as from the introduction of a foreign agent such as serum, vaccine, antigenic substance or organism. "Furthermore, in contrast to the wild‐type control, mice with Atp13a1 deficiency in macrophages were more susceptible to VSV or IAV infection, resulting in higher mortality following infection." (PMID 36216581, 2022).
neurological disorders (1 paper, 2013). "Since ATP13A1 is highly expressed in developing neuronal tissues and in the brain, this should help in the study of Mn2+-dependent neurological disorders." (PMID 24392018, 2013).
ATP13A1 also shares sentences with these, for which no sentence is quoted: Alzheimer disease (1 paper); cancer (1); inflammatory bowel disease (1); rheumatoid arthritis (1); schizophrenia (1); Tics (1); type 1 diabetes (1).